SLC22A17 (solute carrier family 22 member 17)
Description:
Cell surface receptor for LCN2 (24p3) that plays a key role in iron homeostasis and transport. Able to bind iron-bound LCN2 (holo-24p3), followed by internalization of holo-24p3 and release of iron, thereby increasing intracellular iron concentration and leading to inhibition of apoptosis. Also binds iron-free LCN2 (apo-24p3), followed by internalization of apo-24p3 and its association with an intracellular siderophore, leading to iron chelation and iron transfer to the extracellular medium, thereby reducing intracellular iron concentration and resulting in apoptosis (By similarity).
Synonyms: 24p3R; NgalR; BOCT; BOIT; NGALR2; NGALR3; hBOIT
Tractability: Small molecule: it belongs to a druggable protein family. Antibody: UniProt places it where antibodies can reach, with high confidence; its Gene Ontology location is reachable by antibodies, with high confidence; UniProt predicts a signal peptide or a membrane-spanning region. PROTAC: its protein half-life has been measured.
Gene: Protein-coding gene on chromosome 14 (23,346,314 to 23,352,912, reverse strand). Ensembl gene ENSG00000092096.
Subcellular location: Cell membrane; Vacuole membrane
Pathways (Reactome):
Transport of small molecules: Iron uptake and transport
Gene Ontology:
Molecular function: protein binding; transmembrane signaling receptor activity; transmembrane transporter activity
Biological process: intracellular iron ion homeostasis; siderophore transport; transmembrane transport
Cellular component: organelle membrane; plasma membrane; membrane; vacuolar membrane
Genetic constraint (gnomAD): Loss-of-function variants: 37 observed, 49.77 expected, observed/expected ratio (o/e) 0.74, 90% interval 0.57 to 0.98. The upper end of that interval is the gene's LOEUF score, 0.98, which puts it in group 4 of 6, group 1 being the genes least tolerant of losing a copy. Missense variants: 651 observed, 690.33 expected, observed/expected ratio (o/e) 0.94, 90% interval 0.88 to 1.01. Synonymous variants: 342 observed, 304.47 expected, observed/expected ratio (o/e) 1.12, 90% interval 1.03 to 1.23.
Homologues: Orthologues: dog SLC22A17 (98% identical), pig SLC22A17 (98% identical), guinea pig SLC22A17 (96% identical), mouse Slc22a17 (96% identical), rat Slc22a17 (96% identical), rabbit SLC22A17 (88% identical), chimpanzee SLC22A17 (85% identical), macaque SLC22A17 (82% identical), Drosophila melanogaster CG42269 (19% identical), Caenorhabditis elegans oct-1 (18% identical), Drosophila melanogaster CG14855 (18% identical), Drosophila melanogaster CG10486 (18% identical), and 36 more. Paralogues in human: SLC22A23 (28% identical), SLC22A31 (28% identical), SLC22A8 (21% identical), SLC22A7 (21% identical), SLC22A1 (20% identical), SLC22A3 (20% identical), SLC22A6 (20% identical), SLC22A12 (19% identical), SLC22A13 (19% identical), SLC22A11 (19% identical), SLC22A2 (19% identical), SLC22A10 (18% identical), and 10 more.
Diseases named in the same sentence as SLC22A17 in open-access papers:
SLC22A17 is named in the same sentence as 59 diseases in open-access papers, as found by Europe PMC text mining. Sharing a sentence is not in itself a finding about the gene and the disease. The quoted sentences say what the papers report.
gastric cancer (7 papers, 2020 to 2024). A primary or metastatic malignant neoplasm involving the stomach. "APOD and SLC22A17 are dysregulated and can be used for prognosis in gastric cancer patients." (PMID 34306002, 2021). "These all indicate that SLC22A17 may influence prognosis through influencing immune cell infiltration and provided further evidence that SLC22A17 may play the same role in gastric cancer." (PMID 32164594, 2020). "Two authors have also reported that SLC22A17 could be a prognosis biomarker of gastric cancer." (PMID 34306002, 2021). "It was found that expression of SLC22A17 (HR = 1.58 (1.18–2.12), P = 0.0022) was associated with worse overall survival (OS) for gastric cancer patients,expression of SUPV3L1 (HR = 0.6 (0.45–0.8) P = 0.00034) was associated with good overall survival (OS) for gastric cancer patients." (PMID 32164594, 2020). "Over the years, it was widely demonstrated that the activation of the SLC22A17 gene partners (NGAL and MMP-9) may promote different malignancies, including glioma, endometrial cancer, lung adenocarcinoma, and gastric cancer." (PMID 39358721, 2024).
glioma (5 papers, 2015 to 2024). A benign or malignant brain and spinal cord tumor that arises from glial cells (astrocytes, oligodendrocytes, ependymal cells). "Previous studies demonstrated that the aberrant expression of SLC22A17 is strictly associated with poor clinical outcomes in patients with endometrial carcinoma, glioma, and hepatocellular carcinoma (HCC)." (PMID 39358721, 2024).
endometrial carcinoma (4 papers, 2016 to 2024). A malignant tumor arising from the epithelium that lines the cavity of the uterine body. "We previously identified LCN2 as an up-regulated gene in endometrial carcinoma, and found that the overexpression of LCN2 and its receptor, SLC22A17, was associated with a poor prognosis." (PMID 27168162, 2016).
esophageal cancer (3 papers, 2014 to 2025). A primary or metastatic malignant neoplasm involving the esophagus. "In particular, it has been reported that both SLC22A17 isoforms 1 and 2 are bilateral iron transporters, while SLC22A17 isoform 3 could exclusively mediate iron influx in esophageal cancer cells." (PMID 36211450, 2022).
cardiomyopathy (2 papers, 2022 to 2025). A disease of the heart muscle or myocardium proper. "Variants SLC22A17-rs4982753 and SLC22A7-rs4149178 were associated with decreasing risk of cardiomyopathy in Canadian CCS (p = 0.0078 and 0.0034, respectively) and were validated in a replication cohort (p = 0.0071 and 0.047, respectively)." (PMID 40413218, 2025). "Different variants in the Solute carrier (SLC) transporters: SLC28A3, SLC22A17, SLC22A7, and SLC22A6 were identified as associated with cardiomyopathy in CCS." (PMID 40413218, 2025). "Most research was done on doxorubicin-induced cardiomyopathy and for seven genetic variants in CELF4, GPR35, HAS3, RARG, SLC22A17, SLC22A7 and SLC28A3, replication studies were performed without consistent results." (PMID 36536332, 2022).
Insulin resistance (2 papers, 2022 to 2025). Increased resistance towards insulin, that is, diminished effectiveness of insulin in reducing blood glucose levels. "Genes commonly upregulated in the IR-iPSCs when compared to each IS-iPSC group include EGR1 and MFGE8, which were previously associated with insulin resistance, as well as CD74, SEMA6B, SLFN13, TMEM151B, SLC22A17, and AGRN." (PMID 35987697, 2022).
osteosarcoma (2 papers, 2018 to 2022). A usually aggressive malignant bone-forming mesenchymal neoplasm, predominantly affecting adolescents and young adults. "SLC22A7 (Solute Carrier Family 22 Member 7) and SLC22A17 (Solute Carrier Family 22 Member 17) were also in connection with cardiotoxicity among patients with osteosarcoma." (PMID 29970035, 2018).
pancreatic cancer (2 papers, 2024 to 2025). "Interestingly, Gomez-Chou and colleagues also reported that the downregulation of SLC22A17 significantly reduced the mRNA expression levels of the pro-inflammatory cytokines and MMPs in pancreatic cancer cells." (PMID 39358721, 2024).
urinary tract infection (2 papers, 2020 to 2024). "In contrast, SLC22A17 overexpression is associated with a reduced risk of urinary tract infections and renal cancer." (PMID 39358721, 2024). "Interestingly, urinary tract infection decreases Fe accumulation in the distal nephron of hemochromatosis mouse models along with decreased SLC22A17 expression, supporting a role for SLC22A17 in mediating Fe uptake in the distal nephron." (PMID 32984336, 2020).
Alzheimer disease (1 paper, 2023). A progressive, neurodegenerative disease characterized by loss of function and death of nerve cells in several areas of the brain leading to loss of cognitive function such as memory and language. "Our study identified Slc22a17 as a potential drug target to design therapies for interventions to enhance neurogenesis in Alzheimer’s disease and proposed additional candidate genes potentially functioning in the NGFR/p75NTR pathway." (PMID 37429840, 2023).
Anxiety (1 paper, 2024). Intense feelings of nervousness, tension, or panic often arise in response to interpersonal stresses. "The genetic knockdown manipulation of SLC22A17 in mPFC effectively attenuated LCN2-mediated anxiety-like behaviors, whilst the receptor ablation in hippocampus or BLA did not prevented the LCN2 effect." (PMID 38589429, 2024).
COVID-19 (1 paper, 2025). A disease caused by infection with severe acute respiratory syndrome coronavirus 2. "SLC22A31 is a member of the conserved OAT family of solute carriers which also has a closely related member gene SLC22A17 (not reported to be associated with COVID-19 severity so far)." (PMID 40240424, 2025).
cutaneous melanoma (1 paper, 2024). A primary melanoma arising from atypical melanocytes in the skin. "Therefore, the aim of the present study is to explore the role of methDNA in the regulation of SLC22A17 in cutaneous melanoma (CM), used as a tumor model." (PMID 39358721, 2024). "Considering the involvement of SLC22A17 in iron trafficking, the dysregulation of SLC22A17 plays a key role in the development, progression, and drug resistance of several tumors, including cutaneous melanoma (CM)." (PMID 39358721, 2024).
epilepsy (1 paper, 2024). A brain disorder characterized by episodes of abnormally increased neuronal discharge resulting in transient episodes of sensory or motor neurological dysfunction, or psychic dysfunction. "Various solute carriers and transporters are associated with epilepsy, and the severity in Case 2 can be explained by an additional pathogenic variant in SLC22A17, a target gene that is likely to be modulated by RTEL1-TNFRSF6B overexpression via hsa-miR-3569-3p." (PMID 39156922, 2024).
melanoma (1 paper, 2024). A malignant, usually aggressive tumor composed of atypical, neoplastic melanocytes. "The SLC22A17 expression analysis was carried out using two different approaches: (i) comparing the expression levels of All Var, Var 1, 2, and 3 among melanoma cell lines; (ii) comparing the expression levels of SLC22A17 variants within each cell line." (PMID 39358721, 2024). "Interestingly, Var 2 was the most expressed SLC22A17 variant in all melanoma cell lines, except for MeWo, in which Var 1 showed the highest expression levels." (PMID 39358721, 2024). "Among the other melanoma cell lines, A2058 showed the highest SLC22A17 expression levels, followed by A375 cells." (PMID 39358721, 2024). "Since the current literature lacks evidence on the mechanisms responsible for SLC22A17 dysregulation in melanoma, in the present study, we investigated the role of methDNA in the regulation of SLC22A17 in CM." (PMID 39358721, 2024). "Functional studies on melanoma cell lines treated with 5-Azacytidine (5-Aza) were conducted to assess the correlation between methDNA and SLC22A17 expression." (PMID 39358721, 2024). "On these bases, in the present study, the relationship between methDNA and SLC22A17 expression in CM was investigated through computational approaches and further studied in both melanoma cell lines and tissue samples derived from CM patients." (PMID 39358721, 2024). "The RT-qPCR expression analysis of SLC22A17 revealed that WM115 cells showed higher expression levels of SLC22A17 All Vars, as well as Vars 1, 2, and 3 (FC = All Vars: 7.0; Var 1: 5.5; Var 2: 6.5; Var 3: 7.6) compared to other melanoma cell lines." (PMID 39358721, 2024). "Since the 3’UTR region was hypermethylated (≥ 62.9%) in all melanoma cell lines, no relevant regulatory role in SLC22A17 gene expression was observed, indicating that the SLC22A17 expression levels mainly depend on the methDNA status of the promoter and body regions." (PMID 39358721, 2024). "Finally, no significant variation was detected neither for methDNA hotspots nor for the SLC22A17 All Vars/Vars 1, 2, and 3 expression in SK-MEL-28 cells, which were more resistant to 5-Aza treatment compared to the other melanoma cell lines." (PMID 39358721, 2024).
non-small cell lung carcinoma (1 paper, 2024). A group of at least three distinct histological types of lung cancer, including non-small cell squamous cell carcinoma, adenocarcinoma, and large cell carcinoma. "Similarly, SLC22A17 overexpression plays a critical role in the pathogenesis of gastric and non-small cell lung cancer, representing a negative prognostic biomarker for such tumors." (PMID 39358721, 2024).
ovarian carcinoma (1 paper, 2023). A malignant neoplasm originating from the surface ovarian epithelium. "The expression of CYBRD1, LRP2, TFRC, SLC22A17, HEPH, SLC39A14, and PCBP2 involved in iron import was associated with poor OS of ovarian cancer, whereas the expression of LCN2, CP, SLC46A1, STEAP3, and LTF in this process was associated with improved OS in ovarian cancer." (PMID 38186569, 2023).
Pan (1 paper, 2024). "The gene/transcript expression and methDNA profiling of SLC22A17 were also established by analyzing the TCGA Pan-Cancer SKCM datasets." (PMID 39358721, 2024).
tumor (14 papers, 2012 to 2025). "Our results demonstrated that LCN2 and MMP9 were mainly upregulated in most tumor types, whereas SLC22A17 was largely downregulated, representing a specific hallmark signature for all gastrointestinal tumors." (PMID 36211450, 2022). "We found that tumor-derived LCN2 activated astrocytes through SLC22A17 and JAK2/STAT3 signaling, leading to the secretion of macrophage-recruiting chemokines." (PMID 41436606, 2025). "Since LCN2 is a secreted protein, the possibility exists that iron-loaded LCN2 is rapidly captured by tumor cells due to the enhanced expression of SLC22A17, the LCN2 receptor." (PMID 40109379, 2025). "In this context, our previous research showed the role of methDNA in the modulation of the NGAL/SLC22A17/MMP-9 network in several tumor types." (PMID 39358721, 2024). "When correlation analysis was carried out in tumor samples, SLC22A17 was negatively correlated with both LCN2 and MMP9, showing few correlation pairs compared to those obtained for normal samples." (PMID 36211450, 2022). "In particular, further investigations should be carried out to better clarify the relationship between SLC22A17 and iron metabolism, whose imbalance either promotes tumor growth or induces oxidative stress–mediated ferroptosis." (PMID 36211450, 2022). "Overall, differential analysis revealed that LCN2 and MMP9 were widely upregulated in several tumor types, while an opposite trend was observed for SLC22A17, suggesting its potential role in tumor suppression." (PMID 36211450, 2022). "On the other hand, the expression levels of the SLC22A17 gene and its isoforms were downregulated in tumor samples compared to normal tissues by analyzing collectively all tumor samples or by tumor type." (PMID 36211450, 2022). "Furthermore, tumor-secreted LCN2 can bind to SLC22A17 on tumor cells, activating JAK2/STAT3 signaling and promoting VEGF-A expression and release, which enhances tumor neovascularization." (PMID 41436606, 2025). "LCN2 is a secreted siderophore-binding protein that can capture iron-containing complexes in iron-poor niches and deliver iron to cancer cells via specific receptors (e.g., SLC22A17/24p3R), thereby supporting tumor cell survival and proliferation under limiting-iron conditions." (PMID 41190142, 2025). "Additionally, LCN2 binds to SLC22A17 on tumor cells themselves, activating JAK2/STAT3 and upregulating VEGF-A expression, thereby promoting tumor angiogenesis." (PMID 41436606, 2025). "Several genes involved in the modulation of the tumor microenvironment are regulated by methDNA, including the Solute Carrier Family 22 Member 17 (SLC22A17), which is involved in iron trafficking and extracellular matrix remodeling cooperating with the Gelatinase-Associated Lipocalin (NGAL) ligand." (PMID 39358721, 2024). "The computational analysis showed that the mRNA expression levels of SLC22A17 were significantly lower in CM samples compared to those of nevi samples, suggesting that SLC22A17 may act as a tumor suppressor gene." (PMID 39358721, 2024). "The different prognostic significance of SLC22A17 overexpression in various tumor types leads us to analyze the mRNA expression levels of SLC22A17 in CM, where its clinical implications are still unknown." (PMID 39358721, 2024). "Indeed, the hypomethylation of the SLC22A17 promoter largely observed in tumor samples supported the moderately high SLC22A17 expression found in most tumor types." (PMID 36211450, 2022). "Notably, the cg23464698 and cg16420801, the most frequent probesets correlated to SLC22A17 expression in tumor types, were simultaneously correlated in 11 tumors (green labels)." (PMID 36211450, 2022). "However, since LCN-2 is a secreted protein, the possibility exists that iron-loaded LCN-2 is rapidly captured by tumour cells due to the enhanced expression of SLC22A17, the LCN-2 receptor." (PMID 31772326, 2020).